SIRT1 (sirtuin 1)
Diseases named in the same sentence as SIRT1 in open-access papers (continued):
Sharing a sentence is not in itself a finding about the gene and the disease.
cancer (continued). "SIRT1 plays a crucial role in delaying cellular aging and preventing cancer by regulating DNA repair mechanisms, activating the DNA repair pathway, repairing damaged DNA, and maintaining genomic stability." (PMID 40563894, 2025). "The mechanisms by which SIRT1 influences cell metabolism, aging, cardiovascular disease, inflammation, neurodegenerative disorders, and cancer have been extensively researched." (PMID 40563894, 2025). "The complexity of its regulatory networks, involving miRNAs, m6A modifications, and proteins like SIRT1, underscores the need for further research to develop effective cancer therapies that manipulate autophagy pathways." (PMID 40650051, 2025). "The study suggests that puerarin’s anticancer effects are mediated through the downregulation of SIRT1, leading to increased apoptosis in resistant cancer cells." (PMID 41300302, 2025). "What’s more, a recent study has revealed that metformin can trigger Caspase3/GSDME-mediated pyroptosis of cancer cells by activating the AMPK/SIRT1/NF-κB pathway." (PMID 40894196, 2025). "The resistance of SIRT1 to both proliferation and apoptosis is consistent with its role in inducing G1 phase arrest and its reduced activity in certain cancers." (PMID 40338031, 2025). "In the research on SIRT1’s role in inhibiting cancer, two molecules, β-catenin and NF-κB, are particularly crucial." (PMID 40567502, 2025). "miR-34a-5p targets many signaling molecules such as BCL2, CCND1, and SIRT1 that have a key role in the biological activities of cancer cells." (PMID 40061926, 2025). "SIRT1 inhibitors have emerged as promising therapeutic agents for disrupting cancer cell survival and promoting apoptosis." (PMID 41008982, 2025). "SRT1720 is a synthetic small molecule SIRT1 activator that has anti-cancer activity in preclinical models." (PMID 41304967, 2025). "A deeper understanding of how SIRT1 regulates cancer cell survival, proliferation, migration, and drug resistance is essential to optimize therapeutic strategies." (PMID 41008982, 2025). "Similar to CRC, SIRT1 exhibits a dual role in GC, with evidence supporting both its promotion and inhibition of cancer progression." (PMID 40567502, 2025). "In conclusion, the dual roles of SIRT1 in gastrointestinal tumors present both challenges and opportunities for cancer research and therapy." (PMID 40567502, 2025). "Several SIRT1 inhibitors, such as EX-527 and nicotinamide, are currently in clinical trials and show promising outcomes in reducing cancer cell proliferation and improving chemotherapy response." (PMID 41008982, 2025). "In particular, investigating how SIRT1 modulates redox homeostasis and oxidative stress adaptation in cancer cells is critical because redox regulation is closely linked to senescence evasion, metabolic reprogramming, and therapeutic resistance." (PMID 41008982, 2025). "Over 70 clinical trials focusing on SIRT1 activation by 1 in a variety of medical conditions (e.g., cancer, metabolic, neurological, and cardiovascular disease) have been undertaken in recent years, with many of them still continuing." (PMID 39215785, 2025).
cancer (continued). "In hypoxic tumor microenvironments, AMPK and SIRT1 enhance mitochondrial function and metabolic adaptation, allowing cancer cells to survive energy stress." (PMID 39857404, 2025). "Other sirtuin isoforms, such as SIRT1, play contrasting roles to SIRT6 because SIRT1 prevents muscle wasting in response to GC and cancer." (PMID 40806744, 2025). "Firstly, SIRT1 is essential for maintaining the self-renewal and survival of cancer stem cell (CSCs), which are responsible for tumor initiation, metastasis, and therapeutic resistance." (PMID 40052151, 2025). "miR-132 play a cancer promoting role by directly acting on the 3′UTR of SIRT1 mRNA and inhibiting its expression." (PMID 40567502, 2025). "SIRT1 inhibition generally promotes the survival, proliferation, and metabolism of cancer cells, playing an important role in their resistance to treatment." (PMID 40664665, 2025). "In cancer, SIRT1 can be either tumor-promoting or tumor-suppressing, depending on the specific cancer type and stage." (PMID 41304625, 2025). "In cancer, SIRT1 has a controversial role as it has been reported with oncopromoter and oncosuppressor functions." (PMID 38794171, 2024). "SIRT1 expression was significantly reduced in various cancers and was different across molecular and immune subtypes." (PMID 39845948, 2024). "Nevertheless, this study provides a robust foundation for understanding the role of SIRT1 in cancer and offers valuable insights for the future development of precision-targeted therapies and immunotherapies." (PMID 39845948, 2024). "Our results proposed miR-181b and -miR181c as new generation of SIRT1 inhibitors with promising effects on overcoming cancer drug resistance and improve therapeutic outcomes of cancer treatment." (PMID 38598008, 2024). "This review underscores the potential of SIRT1 as a therapeutic target, opening new avenues for enhancing cancer treatment efficacy." (PMID 39403142, 2024). "Propofol’s potential as an anti-cancer agent in reducing tumor metastasis is partly attributed to the downregulation of SIRT1." (PMID 39403142, 2024). "In fact, emerging evidence demonstrated that SIRT1 acts as a resistance-driver gene by epigenetically regulating metabolic and mitochondrial gene signatures in cancer, including BTC." (PMID 38598008, 2024). "Specifically, our analysis revealed that SIRT1 was differentially expressed in immune subtypes of 16 cancer types, including BLCA, BRCA, GBM, HNSC, and KIRC." (PMID 39845948, 2024). "Our study aimed to analyze the role of SIRT1 in pan-cancer to gain a more comprehensive understanding of its role in multiple malignancies." (PMID 39845948, 2024). "In cancer tissue, Sirt1 was expressed in 79% whereas it was scarcely present in nearly all normal tissue." (PMID 38427808, 2024). "The interactions between autophagy and apoptosis play a crucial role in human cancers, with SIRT1 acting as a key mediator." (PMID 39403142, 2024). "SIRT1 helps cancer cells survive chemotherapy, SIRT2 inhibits cell growth, and SIRT3 controls mitochondrial health, while SIRT4, SIRT5, SIRT6, and SIRT7 each influence metabolism, angiogenesis, and metastasis." (PMID 39682281, 2024). "In FLU-resistant PCa cells, increased SIRT1 expression contributes to cancer stem cell-like properties and drug resistance." (PMID 39796040, 2024).
cancer (continued). "The results of a recent meta-analysis revealed that high expression of SIRT1 was an independent prognostic factor for prolonged overall survival in patients with malignant tumors." (PMID 39845948, 2024). "Using the CancerSEA platform, we investigated the functional implications of SIRT1 across various types of cancer, revealing a significant correlation between SIRT1 expression and key cellular functions at the single-cell level." (PMID 39845948, 2024). "Our analysis of the correlation between SIRT1 and immune cell infiltration in 33 cancer types yielded results that were consistent with those of previous studies." (PMID 39845948, 2024). "SIRT1, widely studied as a target of miR-132/-212, plays a vital role in the development of cancers, inflammatory diseases, neurological disorders, and other illnesses." (PMID 39494277, 2024). "As a therapeutic target, SIRT1 holds promise for conditions such as cardiovascular diseases, cancer, metabolic disorders, and inflammation." (PMID 38302916, 2024). "Owing to its key role in regulating cellular function, energy balance, and aging, SIRT1 has attracted much attention in a variety of diseases, especially cancer." (PMID 39845948, 2024). "The altered expression and activity of SIRT1 and FOXO3 are closely associated with tumorigenesis and tumor progression in various cancers." (PMID 39266959, 2024). "Both knockdown and pharmacological inhibition of SIRT1 neutralized the effects of ZMIZ1 knockdown on cancer cells." (PMID 38214831, 2024). "SIRT1 in general promotes proliferation in cancers, including PCa, but suppresses growth in glioblastoma and bladder carcinoma." (PMID 39796040, 2024). "Our research highlights the crucial role of SIRT1 in pan-cancer studies and establishes a foundation for uncovering its potential involvement in cancer development and therapeutic strategies." (PMID 39845948, 2024). "Furthermore, SIRT1 mutations may be correlated with the clinical features and prognosis of cancer." (PMID 39845948, 2024). "This study systematically elucidates the role of SIRT1 in pan-cancer from multiple perspectives, including gene expression, prognosis, function, mutation sites, and immune cell infiltration." (PMID 39845948, 2024). "SIRT1 inhibits cancer progression mainly by affecting DNA repair and increasing genomic stability primarily through substrate deacetylation." (PMID 39479446, 2024). "Evidence demonstrates that overexpression of MOF can increase the expression of SIRT1 at both mRNA and protein levels, subsequently inhibiting cancer cell proliferation and migration." (PMID 39598398, 2024). "Increased activity of SIRT1 leads to upregulation of resistance-promoting genes in drug-resistant cancer cell lines, whereas inhibition of SIRT1 with siRNA reduces cell resistance." (PMID 39266959, 2024). "SIRT1-mediated deacetylation of FOXO3a regulates the transcriptional activity of FOXO3a, as well as the proliferation and apoptosis of cancer cells." (PMID 38214831, 2024). "SIRT1's involvement in cancer has been defined by dichotomous roles, demonstrating dual effects as both a tumour suppressor and an oncogene depending on cancer type and stage." (PMID 38597418, 2024). "Disrupting either SIRT1 or MPP8 reverses E-cadherin repression and diminishes the EMT phenotype, emphasizing the integral role of the SIRT1/MPP8 axis in shaping the epigenetic framework that governs cancer cell invasion and metastasis." (PMID 39796040, 2024).
cancer (continued). "The mechanisms and molecular pathways involved in Sirt1 suppression need to be examined further to develop future Sirt-based anti-cancer therapeutics." (PMID 38254877, 2024). "Previous reports have suggested HIF1α to be a target of deacetylation by SIRT1 at Lys 674, which contribute to metabolic reprogramming in cancer cells." (PMID 39693143, 2024). "Given that ccRCC is a cancer with abnormal lipid accumulation and Sirt1 is considered an influencing factor of metabolism, this article aims to investigate the effect of Sirt1 in ccRCC and provide new ideas and methods for the diagnosis and treatment of ccRCC." (PMID 38427808, 2024). "This duality makes SIRT1 inducers promising for cancers where oxidative stress plays a significant role, offering a cytoprotective effect in normal tissues while targeting cancerous growth." (PMID 39403142, 2024). "Despite evidence for a protective role of sirtuins against cancer development, some cancers are also characterized by increased levels of SIRT-1 and cancer cells depend on SIRT-1 for survival and proliferation." (PMID 39497715, 2024). "The AUC values of SIRT1 exceeded 0.7 in 14 cancers, especially in KICH and ESCC, where the AUC values reached 0.923 and 0.902, respectively, indicating extremely high diagnostic efficacy." (PMID 39845948, 2024). "The SUMO E3 ligase PIAS4 is induced by hypoxia and prevents Sp1 from binding to the SIRT1 promoter in cancer cells." (PMID 39497715, 2024). "Among the putative targets for ISGylation, we selected SIRT1, as SIRT1 has been suggested to impact cancer pathogenesis." (PMID 38443596, 2024). "For example, SIRT1 expression was significantly reduced in cancers such as ACC, BLCA, BRCA, CESC, and COAD (p < 0.05), whereas higher expression levels were observed in KIRC, LUAD, and STAD." (PMID 39845948, 2024). "Recent studies have demonstrated that SIRT1 plays diverse roles in tumorigenesis and cancer progression." (PMID 39845948, 2024). "The role of SIRT1 in cancer is controversial and complicated given the multiplicity of its interactions with histones, transcriptional regulators and enzymes and its control of genome stability, cellular differentiation, growth, and metabolism 48,49." (PMID 39494323, 2024). "Disruptions in regulatory factors such as SIRT1, an essential deacetylase involved in various biological activities, can result in metabolic pathway defects, proliferation, and ultimately cancer." (PMID 39012661, 2024). "SPC-180002 is a novel SIRT1/3 dual inhibitor with antiproliferative effects on a wide range of cancer cells by impairing mitochondrial function and redox homeostasis." (PMID 39479446, 2024). "These insights underscore the complex interplay between SIRT1 and autophagy, with significant implications for cancer therapy." (PMID 39403142, 2024). "To assess the prognostic significance of SIRT1 across multiple cancer types, we conducted a KM analysis." (PMID 39845948, 2024). "Belonging to genes regulating drug-resistance in cancer, the presence of the SIRT1 represents a predicted target of particular interest." (PMID 38598008, 2024). "SIRT1 has been reported to promote resistance to platinum‐based agents in human cancers by promoting autophagy." (PMID 39497328, 2024). "SIRT1/2 activation promotes cancer cell differentiation, suggesting that SIRT1/2 is a novel target for treating cancer cells by inducing lipid differentiation." (PMID 37935080, 2024). "Lower SIRT1 expression in luminal epithelium correlates with poor prognosis, promoting cancer progression through the increased acetylation of SOD2 and elevated ROS production." (PMID 39796040, 2024). "Resveratrol induces autophagy in cancer cells by regulating the SIRT1/AMPK pathway, which in turn promotes apoptosis." (PMID 38628201, 2024).
cancer (continued). "Combination therapy with paclitaxel and rubone upregulates miR-34a, enhancing chemosensitivity in resistant cancer cells by targeting SIRT1 and its downstream effectors." (PMID 39796040, 2024). "SIRT1, the best-studied mammalian sirtuin, seems to have a contradictory role in cancer, acting asa tumor promoter or suppressor." (PMID 38261767, 2024). "Intriguingly, alterations in NAMPT levels are associated with metabolic disorders and cancer, while FK866 (a highly specific NAMPT inhibitor that abolishes NAD+ circadian oscillations and SIRT1 cycle activity) can induce apoptosis in human cancer cells." (PMID 39012661, 2024). "Functional enrichment analysis of SIRT1 revealed that SIRT1 regulates cancer development by activating or inhibiting several known key pathways in cancer." (PMID 39845948, 2024). "Studies collectively found that SIRT1 has a role in the pathophysiology of neurological conditions, ageing, cancer and metabolic diseases." (PMID 38416341, 2024). "SIRT1 is capable of activating or inhibiting multiple cancer-related pathways and is intricately involved in immune infiltration and immune regulation." (PMID 39845948, 2024). "To investigate the relationships between SIRT1 and immune infiltration and regulation, we analyzed the correlations between SIRT1 and TILs, as well as immune cytokine markers, across various cancer types." (PMID 39845948, 2024). "With a better understanding of various autophagy regulators now available, this review concentrates on the role of SIRT1 in autophagy regulation within human cancers." (PMID 39403142, 2024). "MiR-29c overexpression in cisplatin-resistant cancer cells was shown to directly target SIRT1 mRNA and suppress SIRT1 expression." (PMID 39403142, 2024). "On the other hand, SIRT1 inhibitors are being explored in cancer types where SIRT1 acts as a tumor promoter, particularly in cases of drug resistance and aggressive cancers." (PMID 39403142, 2024). "Our findings demonstrate a significant difference in the tumor growth rate of EC when the activity of SIRT1 is modulated, thus emphasizing its key role in cancer progression." (PMID 39266959, 2024). "Heterozygous deletion of the Sirt1 gene enhances proliferation, autophagy, stress resistance, and cancer formation." (PMID 38214831, 2024). "It has been shown that SIRT1 (Silent information regulator 2 homolog 1) acts as an oncogene in cancer regulating mitochondrial biogenesis, cellular redox and associated metabolic pathways, and several oncogenic signaling." (PMID 38598008, 2024). "hCCAR2 is generally regarded as a proapoptotic factor, but the SIRT1-dependent role of hCCAR2 in cancer development is still controversial." (PMID 38172598, 2024). "First, we analyzed the mRNA and protein expression of SIRT1 in multiple human organs, tissues, and cell lines and compared its expression patterns in various cancers." (PMID 39845948, 2024). "Providing EVs with AIM2 inflammasome proteins was found to induce pyroptosis in cancer cells by downregulating SIRT1." (PMID 38474460, 2024). "In recent years, there has been growing interest in understanding the regulatory role of SIRT1 in various cancers, including EC." (PMID 39266959, 2024). "Although SIRT1 is primarily seen as an upstream autophagy mediator in cancers, autophagy can also influence SIRT1, impacting tumorigenesis regulation." (PMID 39403142, 2024). "Cox regression analysis of the 33 different cancer types revealed a significant correlation between SIRT1 expression and OS in KIRC and LGG." (PMID 39845948, 2024). "SIRT1, as a key regulator of cellular processes such as DNA repair, apoptosis, autophagy, and metabolism, has become a potential therapeutic target in cancer therapy, where both SIRT1 inducers and inhibitors are being explored for different cancer contexts." (PMID 39403142, 2024).